MIR3140 (microRNA 3140)
Synonyms: hsa-mir-3140; mir-3140
Gene: MicroRNA gene on chromosome 4 (152,489,327 to 152,489,416, reverse strand). Ensembl gene ENSG00000264678.
Homologues: Orthologues: chimpanzee MIR3140 (100% identical).